TBXT (T-box transcription factor T)
Diseases named in the same sentence as TBXT in open-access papers (continued):
Sharing a sentence is not in itself a finding about the gene and the disease.
tumor (158 papers, 2011 to 2026). "The transcription factor brachyury, encoded by TBXT, serves as a critical diagnostic marker and is essential for tumor growth." (PMID 40332566, 2025). "These neoplasms express high levels of a transcription factor, called brachyury (encoded by the TBXT gene), and critically rely on it for survival, thereby qualifying it as a marker and equally relevant as a therapeutic target." (PMID 32752193, 2020). "As the tumours are thought to arise from notochordal remnants, the vast majority of chordomas express the TBXT gene, resulting in detectable nuclear amounts of its gene product brachyury." (PMID 38786326, 2024). "This T-Box transcription factor is commonly recognised as being essential in chordoma cells, and limiting TBXT expression is thought to be the key factor in controlling this tumour." (PMID 38786326, 2024). "They revealed genetic changes in known tumor-related suppressors and oncogenes such as PIK3CA, PTEN and CDKN2A as well as alterations in tissue-specific genes such as TBXT duplications and protein truncating mutations in LYST gene." (PMID 37434245, 2023). "We also observed extensive chromothripsis of the chromosome 6q region encompassing the TBXT gene in one tumor (P63)." (PMID 33536423, 2021). "Brachyury has been found to associate with tumor progression, treatment resistance, and metastasis in various epithelial cancers, and it might play roles in tumorigenesis and aggressiveness in this patient with multiple rare tumors and germ line duplication of the TBXT gene." (PMID 34465320, 2021). "Genomic alterations disrupting the TBXT gene (TBX+) were only observed in four patients, including a patient with germline TBXT duplication, two tumors with somatic focal TBXT duplication, and one tumor with 6q chromothripsis." (PMID 33536423, 2021). "In contrast, gene expression was low in both normal and tumor samples for TBXT and MOS." (PMID 38643219, 2024). "While EDNRB and FMN2 as well as TBXT and ZNF671 could have potential tumor suppressor functions, MOS is a well-known oncogene." (PMID 38643219, 2024).
cancer (99 papers, 2006 to 2026). A tumor composed of atypical neoplastic, often pleomorphic cells that invade other tissues. "Furthermore, overexpression of TBXT induces EMT in a variety of human cancer cells (breast, pancreatic, and lung) and is associated with enhanced secretion of various cytokines, chemokines, and angiogenic factors, especially with induction of the IL-8/IL-8R axis in tumor cells." (PMID 38965548, 2024). "TBXT, a member of the T‐box transcription factor family, drives epithelial‐to‐mesenchymal transition in the metastasis of some cancers." (PMID 40099944, 2025). "Studies in carcinoma cell lines uncovered an autocrine loop between TGF-β1 and BRA/TBXT that induces EMT." (PMID 39769393, 2024). "In addition, TBXT mediates tamoxifen resistance by silencing the expression of sirtuin-1 (SIRT1), an oncogene that has been observed to be overexpressed in a variety of cancers." (PMID 38965548, 2024).
TBXT also shares sentences with these, for which no sentence is quoted: infection (50 papers); COVID-19 (14); primary immunodeficiency (14); colitis (10); asthma (9); psoriasis (8); lymphoma (7); pancreatic cancer (7); syphilis (7); atherosclerosis (6); autoimmune disease (6); acute myeloid leukemia (5); colorectal cancer (5); Immune dysfunctions (5); virus infection (5); colon cancer (4); hepatocellular carcinoma (4); inflammatory bowel disease (4); malaria (4); Sepsis (4); severe combined immunodeficiency (4); Arthritis (3); autoimmune thyroid disease (3); Autoimmunity (3); bone cancer (3); cysticercosis (3); gastric cancer (3); glioblastoma (3); infectious disease (3); lymphopenia (3).
A further 159 diseases each share a sentence with TBXT in 3 papers or fewer.